NCOA4 (nuclear receptor coactivator 4)
Diseases named in the same sentence as NCOA4 in open-access papers (continued):
Sharing a sentence is not in itself a finding about the gene and the disease.
breast cancer (continued). "Paratala and colleagues profiled RET fusions in breast cancer and identified CCDC6-RET, NCOA4-RET and RASGEF1A-RET." (PMID 34650924, 2021). "Among them, ETV6-NTRK3, CCDC6-RET, NCOA4-RET and FGFR3-TACC3 have been reported in breast cancer previously." (PMID 34650924, 2021). "Of note, the vast majority of the 27 fusions we identified were rearranged with novel partners, with only 4 previously reported in breast cancer, including ETV6-NTRK3, CCDC6-RET, NCOA4-RET and FGFR3-TACC3." (PMID 34650924, 2021). "Based on initial detection in two index cases with RET fusions (RASGEF1A-RET and NCOA4-RET), 9693 breast cancers were evaluated for the presence of RET rearrangements as well as missense mutations and copy number changes." (PMID 30446652, 2018). "Importantly, MSCs can induce the spread of cancerous cells; Breast cancer cells treated with MSCs showed overexpression of oncogenes (NCOA4, FOS), proto-oncogenes (FYN, JUN), and EMT-specific markers, leading to breast cancer metastasis." (PMID 37849741, 2023). "Here, the AUs identify RET gene alterations, including known fusions, novel fusions, and rearrangements in breast cancer (BC) that are involved in the tumorigenic process and show the benefit of RET therapy in a recurrent BC patient carrying the NCOA4-RET fusion." (PMID 30446652, 2018). "Therefore, the exact role NCOA4 plays in breast cancer is not fully established and requires further research." (PMID 35311114, 2022).
iron deficiency (22 papers, 2017 to 2025). "The C-terminus of NCOA4 contains a ferritin-binding domain, and this binding is specifically upregulated under conditions of iron deficiency, which are often promoted by iron chelators." (PMID 40943225, 2025). "Under iron deficiency conditions, nuclear receptor coactivator 4 (NCOA4) activates the ferritinophagy pathway (mainly targeting ferritin heavy chain 1) to dynamically release stored iron." (PMID 41311485, 2025). "Conversely, NCOA4 accumulates during iron deficiency, binds to ferritin, and facilitates iron recycling." (PMID 40943225, 2025). "Under conditions of iron deficiency, nuclear receptor coactivator 4 (NCOA4) serves as a selective cargo receptor, binding to ferritin and aiding in its transportation to the autophagosome for subsequent degradation, a process termed ferritinophagy." (PMID 39624950, 2025). "Iron can be recruited from ferritin using ferritinophagy in the case of iron deficiency or increased iron demand, and nuclear receptor coactivator 4 (NCOA4) has been identified as a crucial regulator in ferritinophagy." (PMID 38277217, 2024). "In conditions of iron deficiency, the multifunctional autophagy receptor nuclear coactivator receptor 4 (NCOA4) recognizes ferritin and binds to the autophagic protein MAP1LC3/LC3 (microtubule associated protein 1 light chain 3)." (PMID 39042604, 2024). "For example, analysis of the NCOA4 promoter reveals typical hypoxia response elements through which hypoxia inducible factor 2a (HIF2a) can regulate NCOA4 levels during ischemic hypoxia and iron deficiency." (PMID 39042604, 2024). "Conversely, iron stored in ferritin is released back into the cytosol by the cargo nuclear receptor coactivator 4 (NCOA4) via a degradation process known as ferritinophagy, a process that is activated under conditions of cellular iron deficiency." (PMID 36835406, 2023). "Systemic deletion of Ncoa4 in mice leads to functional iron deficiency, manifested with hematological signatures of iron deficiency anemia despite iron overload in tissues." (PMID 36742433, 2023). "At the transcriptional level, HIF2α promotes the transcript of NCOA4 under hypoxia or iron deficiency circumstances to impact iron homeostasis in the intestine and liver." (PMID 38159858, 2023). "Nuclear receptor coactivator 4 (NCOA4) is a ferritin-specific selective autophagy adapter that ensures a rapid decrease in the level of ferritin in response to iron deficiency." (PMID 37059186, 2023). "In prolonged iron-replete conditions, to prevent iron deficiency caused by excessive iron storage and reduced iron uptake by TfR1, NCOA4 condensates promote the delivery of ferritin to lysosomes." (PMID 37059186, 2023). "Systemic ablation of Ncoa4 in murine models leads to the accumulation of tissue ferritin, reduced systemic iron availability, and a functional iron deficiency that manifests as mild hypochromic microcytic anemia." (PMID 38159858, 2023). "Loss of NCOA4 led to molecular marker changes implying functional iron deficiency and differential gene expressions associated with development of neurons, mitochondrial function, apoptosis, and neurodegenerative disorders." (PMID 36742433, 2023). "In the case of iron deficiency, nuclear receptor coactivator 4 (NCOA4) specifically binds iron-rich ferritin to autophagosomes through FTH1 and transports it to the lysosome to release iron." (PMID 33574983, 2021). "A recent study described the retention of iron within ferritin in NCOA4 knockout (KO) mice, which led to iron-deficiency anemia, highlighting the important role ferritin autophagy mechanism on cellular and systemic iron homeostasis." (PMID 29068390, 2017). "Aberrant splicing may explain the observed uncoupling of ferritin breakdown, where NCOA4 levels accumulate along with a relative cellular iron deficiency." (PMID 40961184, 2025).
iron deficiency (continued). "However, morphological changes, compromised cell viability, and transcriptome profiles of neurodegeneration by NCOA4 depletion were augmented or introduced by coexisting iron deficiency." (PMID 36742433, 2023). "In the case of intracellular iron deficiency, ferritin can also be transported to autophagosome under the action of nuclear receptor coactivator 4 (NCOA4), and ferritin will release Fe3+ again due to autophagy; When cells are not iron deficient, ferritin is degraded through non autophagy." (PMID 36408273, 2022). "In iron deficiency, nuclear receptor coactivator 4 (NCOA4) specifically binds iron-rich ferritin to autophagosomes through FTH1 and transports it to the lysosome for iron release, while NCOA4 can be degraded through ubiquitination, which affects that stability of ferritin." (PMID 34568341, 2021). "In addition, to prevent iron deficiency caused by excessive iron storage in prolonged iron-replete conditions, ferritin is delivered to lysosomes via a noncanonical autophagy pathway mediated by iron (Fe3+)-induced NCOA4 condensation." (PMID 37059186, 2023). "NCOA4 is a key regulator of ferritinophagy and intracellular iron levels—NCOA4-null mice are unable to undergo ferritinophagy and this increased retention of iron within ferritin complexes results in reduced iron export from cells and ultimately in iron-deficient anemia." (PMID 31824960, 2019). "During iron deficiency, DMT1–transferrin and ferritin–NCOA4 systems increase intracellular iron levels via endosomes and ferritinophagy, respectively." (PMID 37107292, 2023). "Quantitative proteomics identified IRP2 accumulation among the most prominent protein responses produced by NCOA4 depletion in HT22 cells, which is indicative of functional iron deficiency." (PMID 36742433, 2023). "Conversely, iron deficiency by deferoxamine (DFO; 100 μM), increased NCOA4 abundance with a concomitant decrease in ferritin protein abundance." (PMID 36290647, 2022). "NCOA4 is required to avoid iron trapping in enterocytes when the demand for iron is high; however, a recent study showed quite surprisingly that in mice with intestine-specific deletions of NCOA4 iron homeostasis is not altered under normal conditions or in iron deficiency." (PMID 38668356, 2024). "Furthermore, we do not know whether a higher proportion of H subunits in a ferritin molecule would support a “faster turnover” under conditions of iron deficiency, nor do we fully understand how the NCOA4-ferritin condensate forms." (PMID 37963965, 2023). "The amount of IRP2 was higher in WT HEK293T cells than in prime-edited HEK293T cells expressing endogenous NCOA4 C410A, indicating that a defect in noncanonical ferritinophagy in WT cells might induce a response typical of cellular iron deficiency in normal culture medium conditions." (PMID 37059186, 2023).
glioblastoma (21 papers, 2021 to 2026). The most malignant astrocytic tumor (WHO grade IV). "In contrast, tripartite motif-containing protein 7 (TRIM7) directly binds to and ubiquitinates NCOA4 in a K48-linked polyubiquitylation manner, facilitating the degradation of NCOA4 and reducing the ferritinophagy and ferroptosis of human glioblastoma cells." (PMID 37497000, 2023). "NR3C1 can act as a direct target of ginsenoside Rg5 to regulate the expression levels of HSPB1 and NCOA4 and inhibit glioblastoma progression." (PMID 40995432, 2025). "For example, modulation of the TRIM7-k48-NCOA4 pathway reduces NCOA4-mediated ferritinophagy in human glioblastoma cells." (PMID 38834843, 2024). "It was observed that cystine deprivation is able to induce NCOA4-mediated ferritinophagy to initiate ferroptosis in T98G and A172 glioblastoma cells." (PMID 37132605, 2024). "Given that NCOA4‐mediated ferritinophagy plays a key role in tumour proliferation and differentiation, researchers have demonstrated COPZ1 downregulation to elevate NCOA4 expression, in turn contributing to ferritin degradation and ferroptosis in glioblastoma." (PMID 38389491, 2024). "TRIM7, which utilizes a K4-linked chain, directly binds to and ubiquitinates nuclear receptor coactivator 4 (NCOA4), thereby reducing NCOA4-mediated ferritin phagocytosis and subsequent ferroptosis in human glioblastoma cells." (PMID 39184045, 2024). "For instance, the inhibition of coatomer protein complex subunit zeta 1 (COPZ1) leads to a decrease in glioblastoma (GBM) cell proliferation through the upregulation of NCOA4 and the facilitation of ferritin degradation." (PMID 38110359, 2023). "For example, loss of COPI coat complex subunit zeta 1 induces nuclear receptor coactivator 4 (NCOA4)-mediated autophagy and ferroptosis in glioblastoma cells." (PMID 35574340, 2022). "TRIM7 modulates NCOA4-mediated ferritinophagy and ferroptosis in glioblastoma cells." (PMID 39193375, 2024). "Elevated NCOA4 expression and ferritin degradation in glioblastoma." (PMID 38389491, 2024). "Similarly, the induction of ferritin autophagy mediated by NCOA4 increases the sensitivity of aggressive glioblastoma cells to ferroptosis." (PMID 37736551, 2023). "Given the already known role of NCOA4 in ferritin degradation, targeting the COPZ1/NCOA4/FTH1 axis may be a promising therapeutic strategy for the treatment of human glioblastoma (GBM)." (PMID 35756082, 2022). "Recent research has shown that Rg5 inhibits glioblastoma progression by activating nuclear receptor subfamily 3 group C member 1 (NR3C1), thereby regulating heat shock protein family B member 1 (HSPB1) and nuclear receptor coactivator 4 (NCOA4)." (PMID 40552277, 2025). "Knockdown of COPZ1 can induce ferritinophagy by increasing NCOA4 and ATG7 expression levels in glioblastoma cells." (PMID 38961066, 2024). "Glioblastoma: Overexpression of TRIM7 inhibits NCOA4-mediated ferritinophagy and ferroptosis through directly binding and ubiquitinating NCOA4 in human glioblastoma cells." (PMID 38072908, 2023). "In contrast, COPZ1 (coatomer protein complex subunit zeta 1) inhibits NCOA4 expression, while silenced COPZ1 increases NCOA4 protein levels and promotes ferritinophagy in glioblastoma multiforme." (PMID 36289191, 2022). "On the contrary, coatomer protein complex subunit zeta 1 (COPZ1) was identified as a promising target for glioblastoma treatment, involving iron metabolism as a critical component of the COPZ1/NCOA4/FTH1 axis, manifesting a negative regulation of expression and activity of NCOA4." (PMID 38961066, 2024).
pancreatic cancer (18 papers, 2018 to 2026). "Mechanistically, ROS induce NCOA4-dependent ferritinophagy and exacerbate mitochondrial and DNA damage, thereby increasing the sensitivity of human pancreatic cancer cells and tumor-bearing mice to chemotherapeutic agents." (PMID 38844964, 2024). "In pancreatic cancer, the upregulation of ferritin autophagy mediated by NCOA4 enhances iron metabolism and promotes tumour growth." (PMID 38853203, 2024). "A recent study reported that NCOA4-dependent ferritinophagy prioritizes the supply of iron to Fe–S cluster synthesis to maintain pancreatic cancer proliferation." (PMID 37059186, 2023). "Pancreatic cancer cell lines have increased NCOA4 levels and a corresponding high flux through the ferritinophagy pathway." (PMID 36160450, 2022). "For example, some researchers have revealed that nuclear receptor coactivator 4(NCOA4)-mediated ferritinophagy, as autophagic process, contributes to ferroptosis via the degradation of ferritin in pancreatic cancer." (PMID 34631790, 2021). "BLU-667 is a highly specific RET inhibitor developed for the treatment of tumors with RET mutations and rearrangements, including NCOA4-RET and CCDC6-RET fusions, as observed in two of the analyzed pancreatic tumors." (PMID 33441414, 2021). "Nuclear receptor coactivator 4 (NCOA4) is a ferritin‐specific receptor that mediates the transport of ferritin to autophagosomes for ferritinophagy, and the knockdown of NCOA4 has been shown to reduce the sensitivity of human fibrosarcoma and pancreatic cancer cells to ferroptosis." (PMID 41560416, 2026). "Meanwhile, low expression of NCOA4 inhibits pancreatic cancer cell death." (PMID 40788949, 2025). "NCOA4-mediated ferritinophagy may contribute to erastin-induced ferroptosis, as recently reported in human fibrosarcoma and pancreatic cancer." (PMID 35433479, 2022). "Like the knockdown of autophagy-related 5 (ATG5) or ATG7, the knockdown of NCOA4 also blocks ferritin degradation and suppresses erastin-induced ferroptosis in fibroblasts and pancreatic cancer cells, whereas the overexpression of NCOA4 promotes ferroptosis by degrading ferritin." (PMID 33117818, 2020). "Notably, pancreatic cancer cell lines have increased NCOA4 expression and a corresponding high flux through the ferritinophagy pathway." (PMID 30360520, 2018). "The degradation of ferritin is mediated by nuclear receptor coactivator 4 (NCOA4)-dependent ferritinophagy in erastin-treated mouse embryonic fibroblasts and human pancreatic cancer cells." (PMID 36845736, 2023). "However, increased NCOA4-mediated ferritinophagy has been shown to help maintain the growth of pancreatic cancer tumors by promoting mitochondrial iron–sulfur cluster protein synthesis and mitochondrial respiration; these different outcomes may be due to different degrees of NCOA4 activation." (PMID 37794028, 2023). "Also, a study on human pancreatic cancer showed that NCOA4 knockout xenografts presented marked tumor growth delay, and PDAC cell lines with NCOA4 depletion after knockdown or clonal knockout demonstrated a marked growth delay due to a significant decrease in free iron." (PMID 39272404, 2024).
ovarian carcinoma (17 papers, 2011 to 2025). A malignant neoplasm originating from the surface ovarian epithelium. "We therefore assessed the expression of NCOA4 splice variants in patient-derived cell lines and ovarian cancer tissue specimens." (PMID 29435183, 2018). "Our findings support a need for further investigations on regulatory mechanisms underlying NCOA4 isoform expression and function in specific subtypes of ovarian cancers." (PMID 29435183, 2018). "Further investigations are needed to elucidate the mechanisms underlying NCOA4 protein dysregulation in ovarian cancer." (PMID 29435183, 2018). "As androgen has been implicated in ovarian cancer, these findings raise the possibility that NcoA4 might play a coactivator role in the etiology/progression in a subset of these cancers." (PMID 22562579, 2012). "This interaction reduces NCOA4 levels, decreases ROS production, and inhibits mitophagy, leading to increased proliferation and invasion of ovarian cancer cells." (PMID 39403142, 2024). "Then, we performed RIP and FISH analysis to verify the targeted binding of these factors after which we constructed ovarian cancer cell models and detected pathway regulator expression (NCOA4)." (PMID 36552889, 2022). "The expression levels of C-MYC and NCOA4 were positively correlated with ovarian cancer malignancy grade." (PMID 36552889, 2022). "In our research, we found that NCOA4 expression was obviously down-regulated in ovarian cancer samples compared with the normal group, and its expression level was negatively correlated with the malignancy of ovarian cancer cases." (PMID 36552889, 2022). "Meanwhile, C-MYC can undergo targeted binding with NCOA4 and inhibit ferritin autophagy and ferroptosis in ovarian cancer cells through the NCOA4 axis, which is consistent with the results of previous studies." (PMID 36552889, 2022). "We transfected SKOV3 cells with plasmids containing RNA mimics and inhibitors (C-MYC and NCOA4) to construct ovarian cancer cell models with different pathway expression states." (PMID 36552889, 2022). "The results showed that compared with ovarian tissues, C-MYC was significantly up-regulated while NCOA4 was obviously down-regulated in ovarian cancer samples." (PMID 36552889, 2022). "Colony formation assays showed that compared with the NC group, the number of cell colonies in the C-MYC over-expression group significantly increased, while this number correspondingly decreased after NCOA4 over-expression in ovarian cancer cells." (PMID 36552889, 2022). "The immunohistochemical staining results confirmed that compared with low-grade ovarian cancer samples, C-MYC showed obvious over-expression and NCOA4 revealed significant inhibition in high-grade ovarian cancer tissues." (PMID 36552889, 2022). "The pathway expression verification confirmed that C-MYC was significantly up-regulated and NCOA4 was significantly down-regulated in ovarian cancer samples, and their expression levels were closely related to tumor malignancy." (PMID 36552889, 2022). "In co-localization analysis we noticed that C-MYC (Green) and NCOA4 (Red) assumed co-localized expression in the cytoplasm of ovarian cancer cells." (PMID 36552889, 2022). "EdU assays revealed that the proportion of new cells in the C-MYC over-expression group obviously increased, while this proportion correspondingly decreased after NCOA4 over-expression in ovarian cancer cells." (PMID 36552889, 2022). "This inhibited ferroptosis, promoted malignant phenotypes and motivated immune evasion in ovarian cancer through NCOA4-mediated ferritin autophagy." (PMID 36552889, 2022). "The role of these isoforms in ovarian cancer remains uninvestigated other than one report of increased NCOA4 mRNA levels in ovarian tumor specimens relative to ovarian surface epithelium (via in situ hybridization)." (PMID 29435183, 2018).